MIR3180-3 (microRNA 3180-3)
Synonyms: hsa-mir-3180-3
Gene: MicroRNA gene on chromosome 16 (18,402,178 to 18,402,271, reverse strand). Ensembl gene ENSG00000266291.
Gene Ontology:
Biological process: miRNA-mediated post-transcriptional gene silencing
Homologues: Paralogues in human: MIR3180-1 (100% identical).